ALKBH5 (alkB homolog 5, RNA demethylase)
Diseases named in the same sentence as ALKBH5 in open-access papers (continued):
Sharing a sentence is not in itself a finding about the gene and the disease.
tumor (continued). "In ALKBH5-knockdown cells, the expression of some genes that are related to angiogenesis as well as cell cycle progression is decreased, which in turn inhibits angiogenesis and tumor progression." (PMID 38053093, 2023). "Overexpression of ALKBH5 increased the tumor burden and resulted in a shorter survival." (PMID 36632222, 2023). "Moreover, FTO and ALKBH5 function as tumor suppressors by inhibiting METTL3 while promoting METTL14 expression." (PMID 37580808, 2023). "To examine whether ALKBH5 was dysregulated in GC tissues, we analysed the entire TCGA GC database, and the results demonstrated that ALKBH5 was highly expressed in 414 GC tumour samples compared to 37 normal gastric mucosa samples." (PMID 36864711, 2023). "Together, these results demonstrate FTO and ALKBH5 inhibits tumor growth in vivo and may participates glucose metabolism." (PMID 37580808, 2023). "This may be related to ALKBH5 inhibiting immune cells in the tumor microenvironment and regulating lactic acid." (PMID 37427112, 2023). "Additionally, treatment of HBAAV‐TBG‐shALKBH5 or/and CCR6 inhibitor markedly decreased tumour volume and liver/body weight ratio, promoted tumour necrosis and inhibited ALKBH5/TIRAP axis in tumour." (PMID 36792369, 2023). "We measured the expression of ALKBH5 in six paired tumor and adjacent tissues by Western blotting." (PMID 37612282, 2023). "Furthermore, the levels of RAB5A mRNA were also increased in tumour tissues and showed a positive correlation with those of ALKBH5 in CRC tissues." (PMID 37203239, 2023). "The local tumor microenvironment as well as transcription factor HOXA10 could stimulate the expression of ALKBH5 in tumor cells 27,28." (PMID 36632222, 2023). "The results showed significant differences in the expression of almost all m6A regulators between tumor and normal tissues, with the majority of m6A regulators being upregulated in WT tissues (P < 0.001), while ALKBH5 and YTHDC1 were downregulated in WT expression levels." (PMID 37735424, 2023). "In addition, IHC experiments showed that the proportion of ALKBH5 and tumor proliferation marker Ki-67 decreased in ALKBH5 knockdown tissues and the proportion of TUNEL-positive cells was increased in the knockdown groups." (PMID 38007439, 2023). "Indeed, accumulating evidence confirmed the biological significance of ALKBH5 in tumor immune responses, cancer cell immune evasion and tumor microenvironment remodeling." (PMID 37915103, 2023). "Y15 blocked ALKBH5 expression by increasing lymphangiogenesis, tumor cell migration, and invasion." (PMID 36632222, 2023). "Unexpectedly, our data suggested that ALKBH5 may act as an oncogenic driver to promote cell metastasis in hypoxia instead of serving as a tumor suppressor in normoxia." (PMID 37149664, 2023). "In addition, in vitro and in vivo studies revealed that ALKBH5 promotes tumor growth, distance metastasis, and suppressed cell death through its m6A catalytic activity." (PMID 38007439, 2023). "A study suggested that ALKBH5 acts as a tumor promoter to participate in the development of CRC." (PMID 37152066, 2023). "However, in some tumors, such as bladder cancer and pancreatic cancer, ALKBH5 was reported to inhibit tumor growth." (PMID 35982895, 2022). "In glioblastoma stem cells, m6A demethylase ALKBH5 is highly expressed, which directly targets the new transcripts of FoxM1 through demethylation, thus increasing the expression of FoxM1, and promoting the stemness and proliferation of tumor cells." (PMID 35022030, 2022). "Moreover, TCGA database analyses of tumor tissues from 33 cancer types showed that ALKBH5 mRNA expression levels were tumor-specific and had the highest expression in Sarcoma." (PMID 35444654, 2022). "In addition, ALKBH5 also functions as a tumor suppressor in clear cell renal carcinoma (ccRCC) and HCC." (PMID 35063010, 2022). "Therefore, ALKBH5 plays an important role in regulating the tumor immune microenvironment and mediating the effect of immunotherapy." (PMID 35945641, 2022).
tumor (continued). "Furthermore, several experimental facts have shown that ALKBH5 is associated with the malignant transformation of cancer, indicating that ALKBH5 inhibitors can be a target of tumor-agnostic therapy." (PMID 35318440, 2022). "Li J showed that in the pathophysiology of ESCC, ALKBH5 acts as a tumor suppressor." (PMID 36386128, 2022). "In our study, knocking out ALKBH5 did not affect tumor growth in immune-deficient NSC mice, emphasizing the pivotal role of m6A modification in regulating the antitumor immune response." (PMID 36566230, 2022). "Moreover, the percentages of NK cells, T cells (CD8+ T and CD4+ T), DCs and M1 macrophages among tumor-infiltrating lymphocytes were significantly reduced after ALKBH5 silencing, and this pattern was reversed after murine IFNα injection." (PMID 35395767, 2022). "In summary, KCNK15-AS1 regulated by ALKBH5-mediated m6A demethylation acted as a tumor suppressor to suppress the malignant progression of PC cells through the KCNK15–AS1/KCNK15 axis and KCNK15–AS1/PTEN/Akt axis, suggesting a promising therapeutic target for PC clinical treatment." (PMID 35936737, 2022). "RNA m6A modification was also found to be involved in the self-renewal of cancer stem cells, tumor metastasis, and drug response/resistance, which encourages us to study other effects of ALKBH5 (or other regulators) on MM for a comprehensive understanding of the roles of m6A modification in MM." (PMID 34759347, 2022). "ALKBH5 promotes OS cell proliferation and tumour growth partially by the ALKBH5–PVT1 axis." (PMID 35735243, 2022). "Here, we found that ALKBH5 may represent a key regulator of tumor metastasis, and its overexpression significant inhibited tumor metastasis." (PMID 35114989, 2022). "ALKBH5 affects tumor growth by regulating cell proliferation, migration, invasion, and metastasis." (PMID 35707365, 2022). "While METTL14, WTAP, METTL3, ALKBH5, and YTHDC2 had lower expression in high risk group, indicating that they might be tumor suppressor." (PMID 35077391, 2022). "Conversely, ALKBH5 also served as a tumor suppressor in some malignancies." (PMID 34759347, 2022). "Similar to other m6A receptors, ALKBH5 acts as a tumor suppressor in a variety of tumors." (PMID 36360287, 2022). "In addition, in vivo experiments have shown that knockdown of ALKBH5 expression impaired tumor formation and reduced BCSC population in breast tumors." (PMID 35628623, 2022). "This study further confirmed the tumor suppressor effect of ALKBH5 both in vitro and in vivo." (PMID 35614935, 2022). "Indeed, m6A regulators have been shown to play the most important role in TNBC; ALKBH5 is remarkably upregulated in TNBC tumor tissues and acts as an independent unfavorable prognostic factor in this cancer." (PMID 36551544, 2022). "According to previous studies, the tumor-promoting or suppressing role of ALKBH5 is largely mediated by a few critical targets, suggesting that modulating the m6A on specific RNAs could alleviate tumor progression with reduced side effects." (PMID 35063010, 2022). "Moreover, tumor-associated macrophages (TAMs), another critical component of the TME, can be recruited and educated by tumor-expressed ALKBH5 under hypoxic conditions." (PMID 35063010, 2022). "IFNα reversed the tumor-promoting capacity mediated by ALKBH5 overexpression in vivo." (PMID 35395767, 2022). "Moreover, ALKBH5 played a complex part in tumor immune microenvironment, mainly manifested in overexpression of PD-L1 on mononuclear macrophage and reduced infiltration of myeloid-derived suppressor-like cells." (PMID 36545327, 2022). "While ALKBH5 has overt oncogenic roles in most cancers, it is a tumor suppressor in others." (PMID 35063010, 2022).
tumor (continued). "Our integrative bioinformatic analysis suggested that the m6A eraser ALKBH5 might play a tumor-suppressive role in NB compared with another m6A eraser FTO." (PMID 35517412, 2022). "This suggested that ALKBH5 regulated tumor immunity in several cancer types." (PMID 35444654, 2022). "Further understanding of regulatory mechanisms on the expression, activation and stabilization of ALKBH5 may provide more ideal targets to up-regulate its level and enhance its tumor-suppressive activities in some cancers." (PMID 35063010, 2022). "We briefly investigated the m6A erasers ALKBH5 and FTO in a dataset including survival data and found that ALKBH5 might play a more prominent role in tumor suppression." (PMID 35517412, 2022). "Indeed, ALKBH5 has been shown to regulate transcriptional modification, maintain mRNA stability, and ultimately promote tumor progression in numerous tumors." (PMID 36513634, 2022). "The possible role of ALKBH5 in the tumor cell stemness of TNBC warrants further investigations." (PMID 36551544, 2022). "Moreover, they also found that miR-193a-3p can directly target ALKBH5 and further promote the apoptosis of tumour cells by inhibiting the mir-193a-3p/ALKBH5/AKT2 signalling pathway in vivo and in vitro." (PMID 35688823, 2022). "In addition, in vitro experiments revealed that blocking YTHDF1 improved the therapeutic effect of anti-PD-L1 in GC cells, and the knockout of m6A demethylase AlKBH5 makes tumor sensitive to anti PD-1 immunotherapy and changes immune cell recruitment." (PMID 36561529, 2022). "Therefore, ALKBH5 is a potential immunotherapy biomarker and predictor of tumor immunotherapeutic response." (PMID 35444654, 2022). "Interestingly, we discovered that in the six pairs of tissues for MeRIP‐seq, the expression of ALKBH5 in tumour tissues was significantly lower than that in normal tissues." (PMID 35979628, 2022). "Similarly, our findings showed that ALKBH5 knockdown in PC9 cells acted as a tumor suppressor by the upregulation of CDKN1A (p21) via m6A alteration." (PMID 35318440, 2022). "Knockout HIFs or ALKBH5 can significantly reduce its tumor initiation ability." (PMID 35022030, 2022). "However, other studies demonstrated that ALKBH5 is actually a tumor suppressor in BC according to cell and animal assays." (PMID 35063010, 2022). "Notably, ALKBH5 shRNA-loaded BMSC-Exos exhibited more inhibitory effects on the tumor growth and metastasis." (PMID 36551544, 2022). "This study initially revealed that ALKBH5 may increase tumor cell stemness and promote TNBC growth and metastasis." (PMID 36551544, 2022). "The tumor growth models showed that ALKBH5 knockdown significantly inhibited tumor growth." (PMID 35031597, 2022). "ALKBH5 acts as a tumor suppressor in PAC, BLC, EC, NSCLC, and HCC." (PMID 35864970, 2022). "Similar to ALKBH5, overexpression of demmethylase inhibits methylation activity, thereby regulating the expression of proto-oncogenes at the post-transcriptional level and inhibiting tumor progression." (PMID 33779693, 2021). "Furthermore, although demethylases’ expression heterogeneity was observed within each subtype, significant differences in FTO and ALKBH5 expression were found among the main tumor subtypes." (PMID 34683137, 2021). "ALKBH5 increased in tumor tissues and predicts a poor prognosis of HBV-HCC." (PMID 34112124, 2021). "Our results provide new insight into the mechanisms involved in ALKBH5-related tumor progression." (PMID 33428593, 2021). "IHC staining showed that only ALKBH5 expression was higher in KL than that of in K tumor tissues." (PMID 34016959, 2021).
tumor (continued). "Interestingly, aberrant hypermethylation of ALKBH5, a gene involved in DNA damage signaling, has been recognized as a unique sign in LS neoplasms compared to CRC sporadic neoplasms." (PMID 34201893, 2021). "Furthermore, ALKBH5 overexpression suppressed tumor growth of Eca-109 cells in nude mice; conversely, depletion of endogenous ALKBH5 accelerated tumor growth of TE-13 cells in vivo." (PMID 34491904, 2021). "M6A modification, FTO and ALKBH5 differed in cellular distribution between tumor samples." (PMID 34683137, 2021). "Furthermore, there are positive correlations between HBx and ALKBH5 in HBV-HCC tissues, and depletion of ALKBH5 significantly inhibits HBV-driven tumor cells’ growth and migration in vitro and in vivo." (PMID 34112124, 2021). "ALKBH5 knockout in tumor cells enhanced the efficacy of immunotherapy, and ALKBH5 could regulate target gene expression and splicing, resulting in changes in metabolite contents and the accumulation of MDSCs." (PMID 34956201, 2021). "Thus, reducing m6A methylation of YAP by ALKBH5 contributes to decreased tumor growth and metastasis by YTHDF2-mediated YAP degradation and miR-107/HuR-mediated YAP inactivation." (PMID 33814008, 2021). "Consequently, both of these actions contribute to impair tumor progression in ALKBH5-overexpressing cells." (PMID 34733841, 2021). "Similarly, the m6A eraser, ALKBH5, can regulate the lactate content, tumor-infiltrating regulatory T cells, and myeloid-derived suppressor cell accumulation in the tumor microenvironment." (PMID 34094986, 2021). "ALKBH5 regulates cell proliferation, migration, invasion, tumor progression, metastasis, tumorigenesis and chemotherapy resistance might by regulating m6A methylation." (PMID 34376206, 2021). "The downregulated expression of m6A regulator ALKBH5 was observed in tumor tissues." (PMID 34868980, 2021). "On the contrary, the depletion of endogenous ALKBH5 remarkably accelerated tumor growth in vivo." (PMID 34491904, 2021). "Furthermore, ALKBH5 expression inversely correlated with the tumor size, lymph node invasion, clinical stage, and histological grade in ESCC patients." (PMID 34491904, 2021). "ALKBH5 m6A reader could regulate the response to anti-PD-1 immunotherapy through inhibiting the accumulation of tumor-infiltrating immune cells." (PMID 34434939, 2021). "Finally, the results showed that the mRNA expression levels of METL14 and ALKBH5 were increased in tumor tissues and RCC cell lines, while the mRNA expression levels of other genes were not significantly changed." (PMID 35126463, 2021). "In conclusion, ALKBH5 functions as a tumor suppressor in the pathogenesis of ESCC." (PMID 34491904, 2021). "The results suggest that expression of ALKBH5, IGF2BP2, METTL16, AL513165.1, and AP005233.2 is significantly associated with tumor stage and that expression of UCA1, IGF2BP2, METTL16, AL513165.1, AP005233.2, and AC099850.3 is significantly associated with tumor grade." (PMID 34233576, 2021). "At the same time, ALKBH5 could serve as a tumor suppressor in the proliferation inhibition of HCC cells." (PMID 33744868, 2021). "ALKBH5 has been regarded as a tumor suppressor in many cancers." (PMID 33015074, 2020). "However, ALKBH5 inhibited tumor growth and metastasis partly through inhibiting the expression and activity of YTHDFs-mediated YAP, and regulating miR-107/LATS2 axis in an HuR-dependent manner." (PMID 32742194, 2020). "In summary, our work has revealed the tumor suppressor properties of ALKBH5 in HCC development." (PMID 32772918, 2020). "In HCC, ALKBH5 is characterized as a tumor suppressor and could attenuate the expression of LYPD1 via an mA-dependent manner in HCC cells." (PMID 33015074, 2020). "A plausible explanation for this paradox might be the tissue-specific expression of ALKBH5, and we suppose that ALKBH5 holds discriminant function in different tumour types by intricate mechanisms with respect to tumourigenesis." (PMID 32429928, 2020).
tumor (continued). "Moreover, the decrease in ALKBH5 and FTO mRNA levels was associated with a decrease in total and tumor-specific survival times after nephrectomy." (PMID 32398132, 2020). "Therefore, m6A demethylase ALKBH5 inhibits tumor growth and metastasis by reducing YTHDFs-mediated YAP expression and inhibiting miR-107/LATS2–mediated YAP activity in NSCLC." (PMID 32106857, 2020). "Similarly, two major RNA demethylases, i.e., FTO and ALKBH5, were overexpressed in the tumor samples." (PMID 33062408, 2020). "Deletion of ALKBH5 sensitizes the tumor against the anti PD-1 treatment and GVAX vaccine." (PMID 33718113, 2020). "Subcutaneous and orthotopic models further uncovered the role of ALKBH5 in tumour growth." (PMID 32429928, 2020). "Similarly, in glioblastoma, GSCs proliferation and tumor formation is disrupted upon ALKBH5 inhibition." (PMID 31921664, 2019). "In addition, 5-fluorouracil (5-FU), LIN28A, let-7, RASSF5, and ALKBH5 were shown as top 5 upstream regulators, all of which have been reported to be related to tumor formation." (PMID 30286143, 2018). "Hence, HIF-dependent ALKBH5 expression mediated enrichment of BCSCs in hypoxic tumor microenvironment." (PMID 29374143, 2018). "In lung cancer models, ALKBH5 regulates the circRNA echinoderm microtubule-associated protein-like 4 (circEML4)/miRNA/suppressor of cytokine signaling 2 (SOCS2) axis, supporting the M2-like function of tumor-associated macrophages and facilitating immune evasion in non-small cell lung cancer." (PMID 41376856, 2026). "Mechanistically, ALKBH5 decreased the m6A modification of Arg-1 mRNA, thereby reducing its stability and protein expression, suggesting that ALKBH5 loss in CRC may enhance Arg-1–mediated immunosuppression and tumor progression." (PMID 41562066, 2025). "Interestingly, ALKBH5 can also function as a tumor suppressor in BC." (PMID 40958857, 2025). "In addition, the overexpression of ALKBH5 diminishes the population of tumor‐infiltrating lymphocytes, which could reduce immune surveillance and programmed cell death." (PMID 39802639, 2025). "However, high expression of ALKBH5 can also inhibit ferroptosis, promoting tumor progression." (PMID 40740874, 2025). "Overall, the synergistic mechanisms between ALKBH5 and reader proteins in the digestive system tumors are summarized, while the regulatory factors may have opposing effects on different tumors, as well as within the same tumor in different patients." (PMID 40958857, 2025). "In addition, the context-dependent nature of ALKBH5 activity remains unclear, as its functions may vary across tumor types, genetic backgrounds, and microenvironmental conditions such as hypoxia or metabolic stress." (PMID 41562066, 2025). "Furthermore, it remains unclear whether ALKBH5 can interact with other reader proteins, such as YTHDCs, and HNRNPs, to modulate tumor progression in the genitourinary system, which needs further investigation." (PMID 40958857, 2025). "Besides, the downregulation of ALKBH5 can stabilize PD-L1 mRNA, mediating tumor immune evasion." (PMID 41584846, 2025). "Moreover, ALKBH5 curbs in vivo tumor growth and metastasis by reducing YAP expression and activity." (PMID 39192357, 2024). "Further, METTL14 and the demethylase, ALKBH5, can control the expression of one another, block the demethylase activity of the m6A reader, YTHDF3, and regulate m6A modification levels of angiogenesis-associated transcripts, resulting in tumor angiogenesis and malignant processes." (PMID 39691597, 2024). "Interestingly, FTO and ALKBH5 may act as oncogenes or tumor suppressors in different types of cancer, indicating their diverse roles in tumor progression and metastasis." (PMID 39192357, 2024). "Notably, FTO and ALKBH5 may exert opposing effects within tumor contexts, regulated by factors such as tumor type, microenvironment, and cellular status." (PMID 39192357, 2024). "Similarly, oncogenic and tumour‐suppressive roles of ALKBH5 have been reported." (PMID 38545841, 2024).